INS (insulin)
Diseases named in the same sentence as INS in open-access papers (continued):
Sharing a sentence is not in itself a finding about the gene and the disease.
non-alcoholic fatty liver disease (408 papers, 2004 to 2026). "First, an elevated ALT/AST ratio is a well-established marker for nonalcoholic fatty liver disease, a condition intrinsically linked to hepatic and systemic insulin resistance." (PMID 41239677, 2025). "Brisk walking is associated with improved insulin sensitivity, which lowers the risk for non-alcoholic fatty liver disease and its progression to hepatocellular carcinoma." (PMID 40369483, 2025). "Physical activity not only upregulates BDNF/TrkB/CREB signaling pathway but also increases insulin sensitivity BDNF is a known myokine associated with physical activity in patients with non-alcoholic fatty liver disease." (PMID 36787304, 2023). "Recent studies have also associated APRIL with insulin resistance, lipolysis, brown adipose tissue dependent thermogenesis and nonalcoholic fatty liver disease, suggesting a broader involvement in energy metabolism." (PMID 38002294, 2023). "Meanwhile, non-alcoholic fatty liver disease was associated with psoriasis, particularly among men, as a result of insulin resistance due to an increased level of proinflammatory adipokines." (PMID 37375611, 2023). "For instance, COBLL1, a gene with liver-specific colocalization for fasting insulin and BMI and previously associated with non-alcoholic fatty liver disease, showed decreased expression under both atorvastatin and metformin in the liver." (PMID 35292083, 2022). "Nonalcoholic fatty liver disease is associated with increased ectopic hepatic fat and hepatic insulin resistance." (PMID 36205997, 2022). "The levels of SIRT1 are involved with the insulin sensitivity of cells and, therefore, associated with non-alcoholic fatty liver disease and DM." (PMID 34880765, 2021). "Insulin resistance is defined as a decreased sensitivity of the peripheral tissues to insulin action; it increases the risk of cardiovascular disease, type 2 diabetes, hypertension, and nonalcoholic fatty liver disease (NAFLD)." (PMID 28870184, 2017). "In a large cohort of patients with nonalcoholic fatty liver disease and biopsy proven nonalcoholic steatohepatitis, mild increase in liver fat was associated with significantly impaired hepatic and whole body-insulin clearance." (PMID 27846285, 2016). "Consumption of β-cryptoxanthin possibly prevents nonalcoholic steatohepatitis (NASH), which is suggested to be caused by insulin resistance and oxidative stress from nonalcoholic fatty liver disease." (PMID 24858832, 2014). "Overall, China leads TyG index research, focusing on its connections to insulin sensitivity, body mass index, and hyperuricemia, while the index’s diagnostic and prognostic significance for nonalcoholic fatty liver disease and cardiovascular diseases represents an expanding research frontier." (PMID 39465764, 2024). "In addition, air pollution has been linked to non-alcoholic fatty liver disease as long-term exposure to concentrated ambient PM causes liver inflammation, fibrosis and activation of insulin signaling pathways." (PMID 39734207, 2024). "The analysis indicated that the pharmacodynamic differences might be linked to pathways such as the PI3K/Akt signaling pathway, insulin signaling pathway, nonalcoholic fatty liver disease, TNF signaling pathway, and FoxO signaling pathway." (PMID 39201413, 2024). "Also, a case–control study among 169 patients with non-alcoholic fatty liver disease (NAFLD) revealed that adherence to a diet with high food insulin index was associated with higher levels of FBS, TG, and LDL-C." (PMID 36529727, 2022). "The dramatic reduction in ceramide levels by clozapine, an obesogenic/diabetogenic antipsychotic drug, contrasts with the evidence that increased ceramide levels are a cause of diet-induced non-alcoholic fatty liver disease, while reduced hepatic ceramide levels increases insulin sensitivity." (PMID 29720183, 2018).
non-alcoholic fatty liver disease (continued). "Among SIRTs, SIRT1 plays a pivotal role in cellular defense against oxidative stress and in modulating insulin sensitivity and β-cell function in the context of the pathophysiological network of nonalcoholic fatty liver disease and T2DM." (PMID 41234228, 2025). "has been associated with non-alcoholic fatty liver disease (NAFLD), promoting hepatic triglyceride accumulation by inhibiting AKT phosphorylation, a key event in insulin signaling." (PMID 40650313, 2025). "In the liver, THRSP expression is rapidly induced by stimuli promoting long-chain fatty acid synthesis, such as THs, glucose, and insulin, and it plays a pivotal role in the pathogenesis of non-alcoholic fatty liver disease." (PMID 40055330, 2025). "Pathways with potential relevance to cardiovascular physiology included focal adhesion, heart development, insulin signaling, and nonalcoholic fatty liver disease, among others." (PMID 41009942, 2025). "Eight clusters are still in progress, including #0 (gut microbiota), #1 (hepatocellular carcinoma), #2 (childhood), #3 (transient elastography), #4 (vitamin e), #5 (insulin sensitivity), #6 (nonalcoholic fatty liver disease), #7 (vitamin d)." (PMID 40356777, 2025). "Estrogen decline favors the development and progression of non-alcoholic fatty liver disease in postmenopausal women because of decreased insulin sensitivity, mitochondrial dysfunction, increased inflammation, and fibrogenesis." (PMID 39274315, 2024). "The combination of silibinin and vitamin E complex has been shown to have therapeutic effects on non‐alcoholic fatty liver disease and improve insulin sensitivity." (PMID 38726421, 2024). "PD improved body weight, insulin sensitivity, and glucose tolerance in mice fed a high-fat diet and also prevented non-alcoholic fatty liver disease, reduced blood lipid levels, and increased fecal lipid excretion." (PMID 39108759, 2024). "This modulation impacts hepatocyte insulin resistance and the occurrence of non-alcoholic fatty liver disease." (PMID 38429802, 2024). "Consistent with our findings, administration of SFN (0.56 g/kg) for 6 weeks significantly improved glucose tolerance and insulin sensitivity in male mice with non-alcoholic fatty liver disease." (PMID 38611359, 2024). "Only genes involved in non-alcoholic fatty liver diseases and insulin-signaling pathways showed a decrease in their relative counts in the treated group as compared to the control groups." (PMID 37840722, 2023). "Increased circulating chylomicron remnants are preferentially taken up by the liver, leading to nonalcoholic fatty liver disease and hepatic insulin resistance." (PMID 37304843, 2023). "The purpose of the current systematic review and meta-analysis was to investigate the effects of exercise on liver function and insulin resistance markers in patients with non-alcoholic fatty liver disease." (PMID 37109347, 2023). "Only genes involved in non-alcoholic fatty liver diseases and insulin signaling pathways showed a decrease in their relative counts as compared to the control groups." (PMID 37840722, 2023). "In a phase 1b study, PXL70 inhibited liver adipogenesis and improved glucose metabolism and insulin sensitivity in patients with non-alcoholic fatty liver disease." (PMID 38066566, 2023). "OCA treatment (6 weeks) was well-tolerated and increased insulin sensitivity and reduced markers of liver inflammation and fibrosis in diabetic and non-alcoholic fatty liver disease (NAFLD) patients." (PMID 37111068, 2023). "Instead, the IPFD model ranked the aromatic amino acid tyrosine, whose presence has been an established biomarker for the exacerbation of insulin dysregulation in patients with non-alcoholic fatty liver disease (NAFLD) and diabetic nephropathy." (PMID 36992769, 2022).
non-alcoholic fatty liver disease (continued). "It ameliorates free fatty acid-induced hepatic steatosis and regulates the secretion of insulin, as well as significantly decreased lipid accumulation that leads to non-alcoholic fatty liver disease (NAFLD)." (PMID 36263142, 2022). "At 65 days of age, the different metabolic pathways were lysine degradation, non-alcoholic fatty liver disease, insulin signaling pathway, nicotinate and nicotinamide metabolism, and pentose phosphate pathway." (PMID 36060747, 2022). "Imatinib can enhance the insulin-mediated vasoreactivity of resistance arteries, increase insulin secretion, protect against human beta-cell death, and reduce non-alcoholic fatty liver disease by targeting inflammatory and lipogenic pathways." (PMID 36426222, 2022). "Recent clinical studies have also shown that IKKε/TBK1 inhibitor can improve hepatic steatosis and insulin sensitivity in obese patients with non-alcoholic fatty liver disease (NAFLD) and T2D17." (PMID 35962183, 2022). "Vitexin, on the other hand, is shown to improve insulin signalling in non-alcoholic fatty liver disease (NAFLD) mice through upregulation of insulin receptor substrate-1 (IRS-1) and also its downstream target AKT." (PMID 35458200, 2022). "Supplementation with DHA in children with non-alcoholic fatty liver disease showed a decrease of fatty liver and a significant reduction in pericardiac and visceral fat, and also in triglycerides and fasting insulin after 6 months of treatment." (PMID 35406010, 2022). "This process results in the hypermethylation of genes directly implicated in carbohydrate and lipid metabolism of PI3K, cAMP, insulin, insulin secretion, and diabetic and non-alcoholic fatty liver disease signalling pathways." (PMID 36289459, 2022). "Non-alcoholic fatty liver disease (NAFLD) is another disorder that is associated with both psoriasis and DM as the liver plays an important role in glucose uptake and impairs insulin secretion." (PMID 35888704, 2022). "Pioglitazone, an insulin sensitizer and primarily an anti-diabetic drug, is also prescribed for the treatment of non-alcoholic fatty liver disease." (PMID 33983968, 2021). "In this clinical study, Fouqueray and colleagues demonstrate that PXL70 inhibits hepatic lipogenesis and improves glucose metabolism and insulin sensitivity in non-alcoholic fatty liver disease patients." (PMID 35028615, 2021). "Oral administration of A. actinomycetemcomitans in conjunction with high-fat diets in mice showed signs of non-alcoholic fatty liver disease (NAFLD) exacerbation through dysbiotic GI changes as well as higher insulin resistance and glucose intolerance." (PMID 33652903, 2021). "Pio has beneficial effects on insulin sensitivity and nonalcoholic fatty liver disease (NAFLD) in experimental animal models, and this drug is approved for treatment of insulin-resistant diabetes in humans." (PMID 32963510, 2020). "Pathogenesis of non-alcoholic fatty liver disease is centered on increased hepatic lipogenesis and decreased hepatic lipolysis in the setting of hepatic and systemic insulin resistance." (PMID 32175323, 2020). "Knockout experiments on mice show that hepatocyte EGR1 helps maintain hepatic insulin response, and as a result, the loss of EGR1 in hepatocytes can contribute to liver steatosis leading to non-alcoholic fatty liver disease development." (PMID 32541819, 2020). "Previous studies demonstrated that miR-185 protected against low insulin sensitivity and liver steatosis in non-alcoholic fatty liver disease." (PMID 32760272, 2020). "Polyphenol-rich virgin olive oil or olive oil without polyphenols in HFD-fed rats limits the HFD-induced resistance of insulin, inflammation, and hepatic oxidative stress, and thus prevents nonalcoholic fatty liver disease progression." (PMID 34466471, 2019).
non-alcoholic fatty liver disease (continued). "Other possible explanations for variability of response phenotypes have included baseline insulin secretory capacity, insulin resistance or the presence of non-alcoholic fatty liver disease." (PMID 30971951, 2019). "Functional enrichment analysis indicated a relationship between insulin, insulin resistance, adipocytokine signaling pathway, and non-alcoholic fatty liver disease for PRKAG2 gene, a target gene of bta-miR-2419-5p." (PMID 31354792, 2019). "Alterations in the expression and methylation patterns of genes involved in insulin signaling as well as those related to specific non-alcoholic fatty liver disease (NAFLD) were also observed in liver biopsies after bariatric surgery." (PMID 31040824, 2019). "Here, we reported that 1-month BBR intervention increased BAT mass and activity, reduced body weight, and improved insulin sensitivity in mildly overweight patients with non-alcoholic fatty liver disease." (PMID 31197160, 2019). "Inhibition of mINDY reduced hepatic lipid accumulation, improved hepatic insulin sensitivity, and prevented diet‐induced nonalcoholic fatty liver disease in adult C57BL6/J mice." (PMID 29928578, 2018). "These substances antagonize the progression of non-alcoholic fatty liver disease, by intervening in various therapeutic targets: oxidative stress, insulin resistance, liver fat accumulation and mitochondrial dysfunction." (PMID 28125040, 2017). "Fructose consumption is a potential factor that induced hepatic de novo lipogenesis resulting in non-alcoholic fatty liver disease and hepatic insulin resistance." (PMID 29046729, 2017). "Pioglitazone, a selective ligand of peroxisome proliferator-activated receptor gamma (PPARγ), is an insulin sensitizer drug that is being used in a number of insulin-resistant conditions, including non-alcoholic fatty liver disease (NAFLD)." (PMID 26035752, 2015). "Irisin has emerged as a potential therapeutic target in metabolic diseases including non-alcoholic fatty liver disease (NAFLD), in which insulin resistance plays a major pathogenic role." (PMID 25514415, 2014). "With accumulating investigations and review articles suggesting PANDER influences T2D and nonalcoholic fatty liver disease by manner of selective hepatic insulin resistance." (PMID 25217499, 2014). "Conversely, treatment with synthetic specific FXR agonists improved insulin sensitivity in rodents, and in patients with non-alcoholic fatty liver disease." (PMID 21736725, 2011). "Non‐alcoholic fatty liver disease (NAFLD), or recently termed as metabolic dysfunction‐associated fatty liver disease (MAFLD), is a progressive metabolic condition characterised by hepatic lipid accumulation, inflammation, fibrosis and insulin resistance." (PMID 41169094, 2025). "Consequently, excess adipose tissue, non-alcoholic fatty liver disease (NAFLD), abnormal cholesterol levels, and impaired insulin sensitivity can increase susceptibility to cardiovascular disease." (PMID 39825321, 2025). "Recent studies have highlighted that an elevated ALT/AST ratio, commonly suggestive of non-alcoholic fatty liver disease (NAFLD), is associated not only with hepatic dysfunction, but also with systemic metabolic disturbances, including insulin resistance and chronic low-grade inflammation." (PMID 40606025, 2025). "Biomarkers, such as glucose, insulin, lipids, and liver enzymes, have been quantitatively analyzed for the diagnosis and follow-up of metabolic disorders, including diabetes mellitus, dyslipidemia, and non-alcoholic fatty liver disease (NAFLD)." (PMID 40141854, 2025). "These disruptions in adipose tissue function not only contribute to the prevalence of non-alcoholic fatty liver disease in obese, insulin-resistant, and diabetic individuals but also impact insulin secretion by inhibiting β-cell potassium channels and altering ATP production." (PMID 38826152, 2024).
non-alcoholic fatty liver disease (continued). "Six of the key metagenes—INSR, MAP3K5, NDUFB8, NDUFS1, SDHB, and UQCRC2—are involved in nonalcoholic fatty liver disease (hsa04932), which is caused by a defect in insulin suppression of free fatty acid (FAA) disposal due to the induction of insulin resistance." (PMID 36979367, 2023). "A meta-analysis that evaluated the effects of thiazolidinediones for the treatment of patients with prediabetes or T2DM combined with Nonalcoholic fatty liver disease (NAFLD) found that pioglitazone significantly improved insulin sensitivity and the results of liver histology." (PMID 38138975, 2023). "Furthermore, in the long term, in mice, LCDs induced non-alcoholic fatty liver disease and decreased insulin sensitivity, which should alarm the scientific community." (PMID 36837859, 2023). "miR-881-3p was identified in certain insulin secretion and age-related functional pathways in aged nonalcoholic fatty liver disease rats and was found to be differentially expressed in the hippocampi in response to chronic high-dose alcohol administration in rats." (PMID 35154330, 2022). "Recently, Xiong and Zhu reported that soy diet could significantly reduce HOMA IR and increase insulin in patients with non-alcoholic fatty liver disease." (PMID 35811988, 2022). "Non-alcoholic fatty liver disease (NAFLD) is characterized by excessive triglyceride and fatty acid accumulation of liver (fat accounts for more than 5% of the liver's weight) not caused by alcohol, excessive oxidative stress, and defective insulin signaling." (PMID 35252271, 2022). "Furthermore, the concentration of TCA cycle metabolites, especially citric acid, was reported to be higher in patients of non-alcoholic fatty liver disease with high insulin sensitivity than those with low insulin sensitivity." (PMID 35425793, 2022). "Furthermore, AT insulin resistance in muscle tissue plays a key role in the development of metabolic and histological abnormalities in obese patients with non-alcoholic fatty liver disease (NAFLD)." (PMID 34780545, 2021). "Increased triacylglycerols’ (TAG) synthesis, insulin resistance, and prolonged liver lipid storage might lead to the development of non-alcoholic fatty liver disease (NAFLD)." (PMID 34202667, 2021). "Furthermore, increased levels of mIndy expression are associated with non-alcoholic fatty liver disease (NAFLD) in obese, insulin-resistant humans." (PMID 34677421, 2021). "Previous in vitro and in vivo studies have shown that Maresin 1 improves insulin sensitivity in diet-induced obese mice, delays the progression of non-alcoholic fatty liver disease, plays a protective role in a mouse model of colitis, and ameliorates Treg/Th17 imbalance in rheumatoid arthritis." (PMID 35083231, 2021). "Thus, the R72TP53 is more active in fat deposition, nonalcoholic fatty liver disease, adipose tissue inflammation, and insulin resistance as compared to P721P53." (PMID 33490239, 2020). "Also, prior reports have shown that OSA-mediated chronic intermittent hypoxia (CIH), triggered by repetitive episodes of apneas and hypopneas, exacerbates metabolic dysfunction including insulin resistance and nonalcoholic fatty liver disease." (PMID 32831639, 2020). "The change in gut microbiota promotes the development of non-alcoholic fatty liver disease by facilitating processes of inflammation, insulin resistance, bile acids and choline metabolism, changing intestinal permeability, production of ethanol in the intestine and interaction with innate immunity." (PMID 31906096, 2019). "Although the pathogenesis of nonalcoholic fatty liver disease is not completely understood, it is thought to be the hepatic manifestation of the dysregulation of insulin-dependent pathways leading to insulin resistance and adipose tissue accumulation in the liver." (PMID 29563854, 2018).